CD40 (CD40 molecule)
Diseases named in the same sentence as CD40 in open-access papers (continued):
Sharing a sentence is not in itself a finding about the gene and the disease.
tumor (continued). "The application of targeting CD40 in cancer immunotherapy recently can be foreseen as the development of tumor immunity research, through irritating Th1 immunity via maturing dendritic cells and driving M2 to M1." (PMID 33505964, 2020). "As DCs have an enhanced capacity to take-up antigens when immature, chemotherapy followed by CD40 activation but not vice versa, elicited effective T-cell dependent immunity in tumor-bearing mice compared with anti-CD40 alone." (PMID 35582441, 2020). "As a cell surface secretory molecule, CD40 has a high sensitivity to reflect the biological changes of cells and can predict the biological behavior of tumor cells in the early stage." (PMID 32411234, 2020). "For example, dual targeting of suppressive myeloid populations by inhibiting CSF-1/CSF-1R signalling and activation of APCs with CD40 agonists conferred superior anti-tumour efficacy and increased survival compared with monotherapy." (PMID 31973030, 2020). "The significance of CD40 in tumor immunology was highlighted by a series of pioneering articles that showed that administering an agonistic antibody induced protective T cell immunity in murine cancer models of T-cell lymphoma and renal carcinoma." (PMID 35582441, 2020). "Flt3L regulates cDC development from myeloid progenitors and, when combined with CD40, can stabilize tumor growth in a murine model." (PMID 33198059, 2020). "CD40 ligation has resulted in a tumor growth-inhibitory effect, delivering potent apoptotic signals to carcinoma cells." (PMID 32331490, 2020). "In contrast, the combination of MEKi/PD-1 suppressed the tumor growth in our PDA tumor model with comparable efficiency as MEKi/CD40 Ab." (PMID 33024933, 2020). "In this tumor model, only the MEKi/CD40 Ab combination resulted in long-term control of tumor outgrowth." (PMID 32358491, 2020). "IDO1 expression was specifically increased in the tumor endothelial pool following anti-CD40 treatment of B16-F10 tumors, whereas it was almost undetectable in the unbound fraction." (PMID 32231867, 2020). "Examination of this tumor system was extended by evaluating TRAMP-C2 administered on each flank with anti-CD40 administered intratumorally in one flank tumor and IL-15 administered systemically." (PMID 32508818, 2020). "LAG3, TIM3, ICOSLG, VISTA, GITR and CD40 were all detected in a majority of the 20 tumor subcohort over an abundance range between 10- and 40-fold." (PMID 32555523, 2020). "Secondly, MEKi treatment can induce immunogenic tumor cell death and together with the CD40 Ab can modulate the immune cell infiltrate towards an immune permissive state." (PMID 33024933, 2020). "In a breast cancer model, expansion of adoptively transferred tumor antigen-specific T cells was mediated by DC engagement through a combination therapy of Flt3L, radiotherapy, poly(I:C), and a CD40 agonist." (PMID 33584701, 2020). "Stimulation with CD40 agonists has been shown to stimulate the T cell priming abilities of DCs and lead to potent anti-tumor T cell immunity in pre-clinical models." (PMID 33101304, 2020). "Depletion studies in murine lymphoma models indicate that DCs—not B cells or macrophages—are indeed the major antigen presenting cell (APC) required for durable anti-tumour immunity, demonstrated when RT is combined with stimulatory CD40 mAb." (PMID 33148287, 2020). "As for CD40 agonists, which are activators of antigen-presenting cells (such as macrophages), a regional involution of the tumor stroma with a decrease in collagen I content after treatment with CD40 agonist was reported." (PMID 33194476, 2020). "When CD40 agonist was administered, we observed a significant reduction in the number of Tregs within the tumor, as confirmed by others in other solid tumor models." (PMID 32821382, 2020). "Our study suggest that CD40 activation supports the generation of tumor-specific CD8+ Tscm, thus providing new insight into cancer immunotherapy." (PMID 32536922, 2020).
tumor (continued). "We found that agonistic CD40 mAb treatment increased immunosuppression in tumor endothelial cells characterized by up-regulation of IDO1." (PMID 32231867, 2020). "Several markers significantly correlated with CD3 expression in the tumour compartment, including CD40, CD44, CD14, B2M, Tim-3, CD8, CD45RO, and ICOS, potentially implicating other cell lineages in immune-associated anti-tumour activity." (PMID 33261133, 2020). "Agonistic CD40 mAb therapy have broad immunostimulatory effects on immune cells, but can also impact other cells in the tumor microenvironment." (PMID 32231867, 2020). "Progressively, CD40 activation has been thought to resort to macrophages to regress and counteract tumor." (PMID 33505964, 2020). "These LAPTM5-induced tumor-suppressing effects are mediated by the inhibition of the CD40-dependent NFκB pathway activation." (PMID 32582531, 2020). "This rare abscopal effect was consistently observed for a single dose optimized at 6 Gy radiotherapy, in combination with locally delivered anti-CD40 inhibiting tumor growth, or complete remission in all tumor lesions." (PMID 32331490, 2020). "A rapid reduction of tumor volume was observed within one day after TLR3/CD40 stimulation in AT-3 and B16 tumor-bearing mice compared to untreated mice." (PMID 33110069, 2020). "Owing to this complementary drug action, the MEKi/CD40 Ab combination exerts synergistic antitumor efficacy as observed in three different syngeneic tumor models." (PMID 32358491, 2020). "Here it was demonstrated that the combination of CD40 stimulation, WBI and ACT enhanced the proliferation of infused T cells, promoted high levels of tumor inflammation and was associated with tumor regression and prolonged survival of treated mice." (PMID 33101304, 2020). "CD40 stimulation of DCs enhances co-stimulation, leading to expansion of tumor-specific T-cells and further activation of the antigen-presentation machinery in response to the produced IFNγ.3–6 The effect of CD40 receptor engagement is context dependent." (PMID 32231867, 2020). "In contrast, agonistic CD40 mAb therapy did not enhance IDO1 expression in CD45+ leukocytes, and the relative level of expression was considerably lower in leukocytes than what was observed in tumor endothelial cells after agonistic CD40 mAb therapy." (PMID 32231867, 2020). "This is because of the ability of agonist CD40 to activate antigen presenting cells (APCs), for the priming of antigen specific T cells and its capacity to redirect tumor-infiltrating myeloid cells with anti-tumor and anti-fibrotic activity." (PMID 32331490, 2020). "Gene set enrichment analysis revealed that agonistic CD40 mAb therapy increased interferon (IFN)-related responses in tumor endothelial cells, including up-regulation of the immunosuppressive enzyme Indoleamine 2, 3-Dioxygenase 1 (IDO1)." (PMID 32231867, 2020). "The combination of the NK cell-activating interleukin IL-15 and therapeutic antibodies, which engaged the co-stimulatory receptor CD40, improved anti-tumor responses in Panc02 or KPC mouse tumor models." (PMID 33022971, 2020). "In contrast, tumor recurrence was observed in one out of five shLAPTM5 tumors after initial shrinkage due to temozolomide treatment, supporting that LAPTM5 sensitized the CD40-positive U87MG tumor cells to temozolomide." (PMID 32582531, 2020). "Strikingly, we also found that higher proportions of circulating or tumor‐infiltrating CD40+ cDC1s and tumor‐infiltrating CD40+ pDCs predicted better clinical outcome." (PMID 33282290, 2020). "CD40 agonists have been exploited to ameliorate the three immune cell cycle steps: tumor killing, T-cell immunity induction and immunosurveillance activation." (PMID 35582441, 2020). "Systemic CD40 activation abolished tumor-induced immunosuppression and incited T-cell-dependent antineoplastic immunity in PDAC." (PMID 33505964, 2020).
tumor (continued). "Our findings demonstrated that effective induction of antigen-specific CD8+ Tscm with CD40 activation evoked long-term anti-tumor immunity." (PMID 32536922, 2020). "Agonistic anti-CD40 increased antigen presenting cell antigen processing and presentation to prime and activate antigen-specific T cells, yielding successful anti-tumor responses as a monotherapy or a component of combination approaches." (PMID 33584701, 2020). "Since activation of T-cells is associated with enhanced IFNγ production, we investigated if IDO1-expression in tumor endothelial cells in response to agonistic CD40 mAb immunotherapy was related to increased infiltration of activated T-cells." (PMID 32231867, 2020). "While mice treated with either CD40 or TLR3 agonist responded with modest tumor growth delay and increased survival, combined TLR3/CD40 stimulation resulted in superior tumor control and survival in all three tumor models." (PMID 33110069, 2020). "To assess the impact of tumor size in response to agonistic CD40 mAb therapy, we segregated tumor-bearing mice from previous studies according to therapeutic response and assessed the baseline tumor size in each group." (PMID 33597954, 2020). "A recent paper by van Hooren and colleagues demonstrated the up-regulation of ICAM-1 expression on tumor ECs treated with Sunitinib and an agonistic anti-CD40 monoclonal antibody." (PMID 32352958, 2020). "To this end, we irradiated primary or distant tumor in combination with in situ administration of Flt3L and TLR3/CD40 agonists to the primary tumor in mice bearing bilateral AT-3 tumors." (PMID 33110069, 2020). "Combination of DC vaccination with CD40 agonistic mAbs is expected to work in synergy generating tumor antigens for uptake by host DC via direct cytotoxicity as well as activation of those DC through CD40." (PMID 30788290, 2019). "This was accompanied by an increase in the expression of costimulatory factors CD80 and CD40 on APCs in tumor-draining lymph nodes." (PMID 31921384, 2019). "In this line, the combination of IL-2 with anti-CD40 antibody was effective on cancer growth control in two different mouse tumor models by inducing M-MDSC elimination trough Fas-mediated apoptosis." (PMID 31447834, 2019). "Activated by CD154 or IFN-γ, the CD40 pathway in tumor cells induced the production of IL-6, promoting the progression of a variety of tumors." (PMID 31708918, 2019). "In another preclinical trial, it was reported that CD40 activation itself was insufficient to induce a productive antitumor immune response, and required macrophages to rapidly infiltrate the tumor lesions, become tumoricidal and facilitate stroma depletion." (PMID 30987642, 2019). "CD40 expressed on tumor cells can be stimulated by agonist CD40L (CD156) to directly induce apoptotic cell death." (PMID 32082375, 2019). "CD40, a member of the tumor necrosis factor receptor (TNFR) family, and its ligation have been shown to have anti-tumor effect via agonistic anti-CD40 mAbs to either directly kill CD40-positive tumor cells or activate T-cell immune responses." (PMID 30925924, 2019). "Instead, addition of a combined innate and adaptive immunotherapeutic approach with RT and combined IT-IC, anti-CTLA-4, CpG and anti-CD40 was effective against this cold 9464D-GD2 tumor, with some mice achieving complete tumor regression." (PMID 31810498, 2019). "In a murine model of spontaneous PDA (KPC mice), combining chemotherapy with CD40 agonists showed T cell infiltration and neoantigen-specific response and tumor regression." (PMID 30804938, 2019). "The co-stimulatory protein, CD40 is expressed by antigen presenting cells including dendritic cells, monocytes, B cells, endothelium, platelets and some tumor cells." (PMID 31035449, 2019). "Luheshi and coworkers also demonstrated that the combination of an agonist CD40 mAb with PD-L1 blockade significantly delayed tumor growth and increased the overall survival in a murine model." (PMID 30987642, 2019).
tumor (continued). "The CD40 agonist antibody was shown to activate macrophages, which lead to tumor regression and effector T cell infiltration." (PMID 31527414, 2019). "Effective activation of T cells also requires additional ligand binding of co-stimulatory receptors, such as CD40, which is a member of the tumor necrosis factor (TNF) receptor family presented on APCs such as tumor-associated macrophages." (PMID 31540286, 2019). "Our results show that this improved response of immunologically cold 9464D-GD2 to RT and combined IT-IC, anti-CTLA-4, CpG, and anti-CD40 is associated with increased CD4+ T cell infiltration and decreased presence of Tregs within the tumor microenvironment." (PMID 31810498, 2019). "In a mouse model of breast cancer, the administration of TMP195 induced the recruitment and differentiation of immunostimulatory CD40+ TAMs, resulting in tumor reduction." (PMID 31878087, 2019). "All primary HRS cells specifically expressed TNFRSF8 (CD30) and most HRS and bystander cells expressed CD40, highlighting the quality of our data However, only a subset of tumours expressed LTR-driven TNFRSF11A and WNT5A transcripts." (PMID 30546079, 2019). "In preclinical studies, agonistic CD40 antibodies have demonstrated T cell-dependent anti-tumor activity, in particular in combination with conventional chemotherapy and immune checkpoint inhibitors (ICIs)." (PMID 30800125, 2019). "Classically activated TAMs stimulated by bacterial products or anti-CD40 mAbs effectively inhibit tumor growth." (PMID 30938231, 2019). "To test this, we treated tumor-bearing mice, induced with doxycycline for 6–7 weeks, with erlotinib alone or a combination of erlotinib plus the CD40 agonist or anti-PD-1 for 4 weeks, (n = 5–10 mice per group)." (PMID 31291990, 2019). "Agonist anti-tumor activity of anti-CD40 antibodies has previously been proposed to rely on FcγRIIB-mediated antibody cross-linking and promoted signaling in CD40-expressing antigen presenting cells." (PMID 30930905, 2019). "These DRibbles contain tumor specific antigens, and lead to the activation of B cells associated with increased expression of MHC class I and II molecules, CD86 and CD40." (PMID 31086070, 2019). "The CD40 agonists in combination with gemcitabine have been shown to induce anti-tumor T-cell response and transform macrophages in PDAC from a pro-inflammatory status to a tumoricidal phenotype." (PMID 31035449, 2019). "In various murine tumor models, agonistic anti-CD40 antibodies have led to the recovery of tumor immune surveillance, mediated by the reprogramming of TAMs towards M1-polarization and effective anti-tumor activity." (PMID 31878087, 2019). "The administration of Poly I:C matured tumour-infiltrating DCs that were initially in a more immature state and expressed less CD40, CD86 and MHCII, hence eliciting a greater anti-tumour activity." (PMID 31091774, 2019). "Anti-CD40 is an agonist antibody binding to CD40 transmembrane protein expressed on a variety of cells such as macrophages, dendritic cells, and some tumor cells." (PMID 31083581, 2019). "Genes favoring tumor growth and cell proliferation, CD40 and CCNA1 were significantly downregulated in treated cells (p < 0.05)." (PMID 31349612, 2019). "They demonstrated that CD40‐activated macrophages rapidly infiltrated tumors, which became tumoricidal, and facilitated the depletion of tumor stroma." (PMID 30923782, 2019). "Using CD40 agonists to augment T cell response to weakly immunogenic tumor antigens or cold tumors is particularly useful in cancers such as PDA that tend to lack mutational burden and often have no baseline immunogenicity." (PMID 30804938, 2019). "Immunohistochemical staining for CD40 in the cytoplasm and membrane of the tumor cells was noted in 99% and 49% of the cases, respectively." (PMID 31137630, 2019).
tumor (continued). "Another possible explanation is the induction of humoral responses, as the vectors used in this study express tumor antigens and CD40/CD40L interactions are important in controlling B-cell immunity." (PMID 31695037, 2019). "In the immune compartment, CD40 activation on dendritic cells leads to the recruitment of tumor-targeting cytotoxic T-cells, and on B-cells, it stimulates endogenous antitumor mAB production." (PMID 32082375, 2019). "Anti CD40 mAb have direct anti-tumor efficacy which relies on activation of DC to induce anti-tumor T cell responses." (PMID 30788290, 2019). "As previous studies from our laboratory have shown that CD8+ T cells and perforin-associated effector function are important for IL-2/CD40-mediated tumor regression in young mice, this likely contributes to poorer tumor responses by elderly mice to IL-2/CD40." (PMID 30560130, 2018). "In mice with subcutaneous KPC tumors, treatment with anti‐PD‐1 or anti‐CTLA‐4 enhanced the anti‐tumor effects of chemotherapy and agonist CD40 treatment." (PMID 30003190, 2018). "In order to assess the impact of macrophage depletion on T cell function, in vivo anti-tumor CTL analyses was performed in IL-2/anti-CD40 treated mice ± macrophage depletion." (PMID 30459812, 2018). "Elevated IFN-γ expression by CD11c+ cells, and increased CD25 expression by CD8+ T cells suggests these cells are more activated with increased effector function and contribute to IL-2/CD40-induced slowing of tumor growth." (PMID 30560130, 2018). "A complete schedule of IL-2/CD40 (i.e., 5 doses) was less effective in elderly mice (45% tumor regression), compared to young mice (100% tumor regression)." (PMID 30560130, 2018). "Although previous studies administered anti-CD40 systemically, we found that local injection into the irradiated tumor site required five-fold less antibody, and was still effective at generating T cell-mediated immunity." (PMID 30245691, 2018). "We demonstrated that NDES-mediated intratumoral release of agonist monoclonal antibodies, OX40 and CD40, resulted in potentiation of local and systemic anti-tumor immune response and inhibition of tumor growth compared to control." (PMID 30400835, 2018). "Taken together, whilst CD11c+ cells from elderly IL-2/CD40-treated mice have increased capacity to present antigens to T cells, their ability to license tumor-specific T cells appears compromised, relative to young counterparts." (PMID 30560130, 2018). "Inducible MyD88/CD40 is an activation switch that supports NK cell expansion, persistence and anti-tumor activity in vitro and in vivo when paired with autocrine IL-15 expression." (PMID 30400835, 2018). "Experiments are ongoing to assess the efficacy and mechanism of action of this tumor-restricted CD40 agonistic DARPin® molecule." (PMID 30400822, 2018). "Our previous studies demonstrated that IL-2/CD40 immunotherapy induces complete and permanent tumor regression in young mice." (PMID 30560130, 2018). "After two doses, IL-2/CD40 slowed tumor growth rates in both age groups, although the effects in terms of tumor size and weights were more pronounced in young mice, relative to PBS diluent controls." (PMID 30560130, 2018). "Agonist CD40 mAbs can mediate antitumor immunity through multiple mechanisms, including enhancing tumor antigen presentation, activation of tumoricidal macrophages, and direct growth inhibition/killing of CD40- expressing tumor cells." (PMID 30400822, 2018). "Blockade of TGFβ signaling in pancreatic stellate cells promotes radiosensitivity, potentially rendering tumor cells better able to be cleared by CD40-activated local macrophages." (PMID 30245691, 2018). "Marigo and colleagues demonstrated that the CD40/CD40L axis is necessary for tumor rejection mediated by CD8+ T cells in the presence of tumor necrosis factor (TNF) derived from dendritic cells (DCs)." (PMID 29329591, 2018).